FUT8 (fucosyltransferase 8)
Diseases named in the same sentence as FUT8 in open-access papers (continued):
Sharing a sentence is not in itself a finding about the gene and the disease.
breast carcinoma (continued). "However, the exact molecular function of FUT8 during breast cancer progression and whether FUT8 could be a potential therapeutic target remains largely unknown." (PMID 28982386, 2017). "Because core fucosylation may affect cell-surface protein functions including receptor signaling, we further investigated whether blocking core fucosylation of TGF-β receptors by FUT8 knockdown could affect the TGF-β1 signaling pathway in aggressive breast cancer MDA-MB-231 cells." (PMID 28982386, 2017). "Targeting FUT8 could be a potential therapeutic strategy for breast cancer treatment." (PMID 28982386, 2017). "Most importantly, inhibition of FUT8 expression or activity may be sufficient to suppress the mobility, invasiveness, and lung metastasis of breast cancer cells in mouse models, which might shed light on devising therapeutic agents to target breast cancer and likely other cancers." (PMID 28982386, 2017). "Numerous studies have shown that FUT8 is abnormally overexpressed in various tumors such as melanoma, osteosarcoma, hepatocellular carcinoma (HCC), breast cancer, and prostate cancer." (PMID 38256141, 2024). "In the present study, we used loss-of-function experiments and functional proteomics with knocking out FUT8 in MDA-MB-231 and Hs578T breast cancer cells to reveal a broad list of core fucosylated target glycoproteins." (PMID 35303925, 2022). "FUT8 ablation alleviates TGF-β signaling and EMT in breast cancer by inhibiting TGF-β core fucosylation, disturbing breast cancer lung metastasis in mice xenografts." (PMID 35508982, 2022). "FUT8 expression was also correlated with disease-free survival in NSCLC, breast cancer, and colorectal cancer, and with relapse-free survival in pancreatic ductal adenocarcinoma." (PMID 33323540, 2020). "In the present study, we found that the increased expression of FUT8 by fentanyl promoted stemness and EMT in breast cancer cells; whereas downregulated FUT8 and α1, 6-fucosylation level by siFUT8 transfection inhibited stemness and EMT." (PMID 28798691, 2017). "Hence, SNAIL may be a regulator of FUT8 during breast cancer EMT." (PMID 28982386, 2017). "Taken together, our study reveals that fentanyl upregulated FUT8 expression, which increased α1, 6-fucosylation level through activation of Wnt/β-catenin signaling pathway, thereby, induce stemness and EMT of breast cancer cells." (PMID 28798691, 2017). "FUT8 protein level was higher in highly invasive breast cancer cells (MDA-MB-231 and Hs578T) than normal human epithelial cells and low-metastatic breast cancer cells (MCF-10A and T-47D)." (PMID 28982386, 2017). "In conclusion, this study suggested fentanyl upregulated FUT8 and α1, 6-fucosylation level through activation of Wnt/β-catenin signaling pathway, thereby, induce stemness and EMT of breast cancer cells." (PMID 28798691, 2017). "Our results reveal a positive feedback mechanism of FUT8-mediated receptor core fucosylation that promotes TGF-β signaling and EMT, thus stimulating breast cancer cell invasion and metastasis." (PMID 28982386, 2017). "High expression of FUT8 was reported to be the main reason for up‐regulation of expression and protein stability of immune checkpoint B7H3, elevating subsequent immunosuppression and suppressing immune response in breast cancer." (PMID 38279874, 2024). "Information on the relevance of TGIF2 and ASCL1 in FUT8 regulation in breast cancer is still lacking." (PMID 36980181, 2023). "Also, impaired breast cancer cell proliferation and metastasis were observed following CRISPR/Cas9-mediated inactivation of fucosyltransferase 8 (FUT8), a critical positive regulator of cell growth and tumor metastasis core fucosylation of target biomolecules." (PMID 35508982, 2022). "FUT8 plays a role in the fucosylation of transforming growth factor-β (TGF-β) serine/threonine kinase receptor I (TβRI) and II (TβRII) on the cell surface and activates the TGF-β signaling pathway to promote EMT and breast cancer cell invasion." (PMID 35216622, 2022).
breast carcinoma (continued). "FUT8 expression is upregulated upon TGFβ treatment of human breast cancer cells which correlates with EMT of human mammary epithelial cells MCF-10A in vitro and with the invasive ability of breast cancer cells in nude mice." (PMID 34069424, 2021). "In regard to survival prognosis, FUT8 expression level was associated with overall survival in non-small cell lung cancer (NSCLC), breast cancer, diffuse large B cell lymphoma, gastric cancer, and glioma." (PMID 33323540, 2020). "We then examined whether FUT8 expression and α1, 6-fucosylation level could influence the stemness and EMT of breast cancer cell by sphere formation assay and transwell assay, respectively." (PMID 28798691, 2017). "In summary, upregulated FUT8 during TGF-β-induced EMT may represent a novel, vicious feed-forward loop linking core fucosylation and TGF-β receptor signaling to promote EMT and breast cancer progression." (PMID 28982386, 2017). "Our previous study showed that upregulated FUT8 during the TGF-β–promoted epithelial–mesenchymal transition (EMT) represents a pathological feed-forward regulatory mechanism linking core fucosylation with TGF-β receptor signaling to accelerate the EMT and promote breast cancer metastasis." (PMID 35303925, 2022). "Our recent study showed that upregulated FUT8 during transforming growth factor (TGF)-β–induced epithelial–mesenchymal transition (EMT) represents a novel, vicious feed-forward loop linking core fucosylation and TGF-β receptor signaling to promote EMT and breast cancer progression." (PMID 35303925, 2022). "FUT8 expression has been observed in normal human epithelial cells (MCF-10A), low-metastatic breast cancer cell lines (T-47D), and mesenchymal-like highly invasive breast cancer cell lines (MDA-MB-231 and Hss578T), with protein levels highest in the highly invasive breast cancer cells." (PMID 33466384, 2021). "We found that only FUT8, not FUT3, FUT11, POFUT1, or POFUT2, was closely and positively correlated with B7H3 in breast cancer tissues." (PMID 33976130, 2021). "While the mechanistic link between miR-198 and FUT8 has not yet been investigated, it has been shown that circular ERBB2 RNA (circ-ERBB2) promotes breast cancer metastatic process, cellular invasion, and proliferation by competing with miR-198 and miR-136-5p as an endogenous RNA sponge." (PMID 36980181, 2023).
lung carcinoma (27 papers, 2017 to 2025). "The up-regulation of FUT8 expression has been reported in various types of cancer, including pancreatic, colorectal, thyroid, ovarian and lung cancers, and linked to the severity of malignant tumors." (PMID 35237113, 2022). "FUT8 was reported to be highly expressed in a variety of cancers, including lung, colorectal, ovarian, prostate, breast, melanoma and so on, and was associated with the prognosis of lung cancer, colorectal cancer and prostate cancer." (PMID 36611197, 2023). "In lung cancer, FUT8 can globally modify surface antigens, receptors and adhesion molecules and knockdown of FUT8 in aggressive cell lines inhibits in vivo tumour growth and metastasis." (PMID 40387385, 2025). "Utilizing bioinformatics approaches, we have investigated FUT8 in lung cancer, resulting in a more systematic and comprehensive understanding of its role in the disease’s pathogenesis." (PMID 40373023, 2025). "In lung cancer, FUT8 was identified as capable of regulating the cancer-promoting potential of cancer-associated fibroblasts through the modification of EGFR core fucosylation." (PMID 38277230, 2024). "These consistent data indicate that the downregulation of the FUT8 gene in antibody-secreting B cells is induced by coculturing with lung cancer cells, which results in a decrease in the level of core fucose of the N-glycan in IgG." (PMID 37865317, 2023). "Abnormal protein fucosylation has also been found in lung cancer, with FUT8 and POFUT1 proteins being upregulated in blood and tumor tissue of patients with lung cancer." (PMID 37256139, 2023). "This involves the addition of α1,6-fucose to the innermost GlcNAc residue of N-glycans through Fuc-TVIII (FUT8), and overexpression is additionally observed in several cancers, including lung cancer." (PMID 35744954, 2022). "A proposed molecular mechanism linking FUT8 and lung cancer progression involves the nuclear accumulation of β-catenin, which occurs during EMT when cancer cells lose the expression of E-cadherin." (PMID 33466384, 2021). "Knockdown or inhibition of FUT8/suppression of core fucosylation attenuates these signaling pathways, suppressing cancer growth/survival in vitro models of lung cancer and HCC." (PMID 31450600, 2019). "To confirm the function of FUT8 on the 5-FU resistance of tumor cells, we performed the same experiments using another tumor cell model: the Lewis lung cancer cell." (PMID 31022917, 2019). "FUT8 inhibits the malignant behaviors of lung cancer cells and is involved in the regulation of dozens of genes associated with the malignancy through multiple mechanisms." (PMID 29872497, 2018). "FUT8 knockdown significantly inhibited malignant behaviors including in vitro invasion and cell proliferation in lung cancer cells, as well as in vivo metastasis and tumor growth." (PMID 28798691, 2017). "Compared with tumor-adjacent tissue, the mRNA expression level of FUT8 was significantly increased both in lung cancer (n=16) and lung adenocarcinoma (n=13)." (PMID 29228607, 2017). "The FUT8 expression was also markedly increased in lung cancer (n=13) and lung adenocarcinoma specimens (n=9), compared with adjacent noncancerous tissue." (PMID 29228607, 2017). "Our analysis of FUT8 indicates that it may serve as a potential biomarker for lung cancer diagnosis and prognosis, and could represent a therapeutic target for LUAD and LUSC immunotherapy." (PMID 40373023, 2025). "FUT8 was elevated in cancers including liver cancer, pancreatic cancer and lung cancer." (PMID 37946130, 2023). "FUT8-mediated core fucosylation plays an important role in the proliferation and invasion of various cancer cells, including liver cancer, breast cancer, melanoma, pancreatic cancer, endometrial cancer, and lung cancer." (PMID 37196106, 2023).
lung carcinoma (continued). "Previous studies have reported that some glycosyltransferases and glycosidases within TGF-β pathway are tightly related to phosphorylation of TGF-β receptors, such as fucosyltransferase 8 (FUT8) in lung cancer and sialylated N-acetylglucosaminyl-transferase V (MGAT5, 37) in CRC." (PMID 35680565, 2022). "To address the issue of why the core fucose level of IgG decreases in the sera of lung cancer patients and whether the expression of the FUT8 gene is involved in this, we next performed coculture analyses using human lung adenocarcinoma cell line A549 and human B cell lymphoma cell lines." (PMID 37865317, 2023). "Abnormal FUT8-mediated core fucosylation plays an important role in tumor proliferation, invasion and metastasis, and FUT8 may be a potential biomarker and therapeutic target in lung cancer and many other cancers." (PMID 37256139, 2023). "FUT8-mediated core fucosylation of E-cadherin may also be involved in the EMT in lung cancer cells." (PMID 37256139, 2023). "Previous reports have suggested that EGFR is involved in HCV infection and that FUT8 can promote EGFR dimerization and phosphorylation in lung cancer cells." (PMID 38253527, 2024). "One study utilized aggressive lung cancer cell lines (CL1-5 and PC14) and found FUT8 knockdown significantly inhibited their malignant behaviours, including in vitro invasion and cell proliferation, and in vivo metastasis and tumour growth." (PMID 33466384, 2021). "Droplet Digital PCR (ddPCR) was used for quantification of the genes (miRs-21, 210, 486-5p, SNHG1, RMRP, FUT8, and POFUT1) in plasma of a development cohort of 64 lung cancer patients and 33 cancer-free individuals." (PMID 29872497, 2018). "We previously developed three microRNAs (miRs-21, 210, and 486-5p), two long noncoding RNAs (lncRNAs) (SNHG1 and RMRP), and two fucosyltransferase (FUT) genes (FUT8 and POFUT1) as potential plasma biomarkers for lung cancer." (PMID 29872497, 2018). "The upregulated expression of FUT8 has been reported in several cancers, including lung cancer, prostate cancer, hepatocellular carcinoma (HCC) and CRC, demonstrating that FUT8 is involved in biological tumor characteristics and patient outcomes." (PMID 29975776, 2018). "Conversely, the incorporation of core fucose by Fut8 promoted EGFR dimerization and phosphorylation in lung cancer cells." (PMID 28912543, 2017). "Studies have shown that fucosyltransferase 8 (FUT8) is overexpressed in NSCLC and promotes lung cancer progression." (PMID 29228607, 2017). "Furthermore, a circRNA from the FUT8 gene which was found upregulated in cancer cells and further validated in FFPE lung cancer tissues, even at the early stage of the disease." (PMID 35060299, 2022). "Studies have shown that FUT8 is overexpressed in NSCLC and promotes lung cancer progression." (PMID 29228607, 2017). "Interestingly, a number of studies have reported low levels of core fucosylation in gastric cancer cells, giant lung cancer cells, and HCC cells and that the overexpression of FUT8 in those cancer cells suppresses proliferation, tumor formation, and metastasis." (PMID 31450600, 2019).
hepatocellular carcinoma (22 papers, 2016 to 2024). A malignant tumor that arises from hepatocytes. "Loss of FUT8 also down-regulates several cellular signaling pathways to inhibit chemical-induced hepatocellular carcinoma." (PMID 27833472, 2016). "In Huh7.5.1 hepatoma cells, FUT8 overexpression activates the PI3K/Akt/NF-κB signaling pathway, resulting in resistance to 5-FU." (PMID 38256141, 2024). "As the core fucose is involved in receptor endocytosis, knockdown of FUT8 or upregulation of FUT8 expression changed the level of bio-nano capsule incorporation into hepatoma cells." (PMID 37061516, 2023). "Other studies have indicated inversely correlated levels of miR-26a, miR-34a, and miR-455–3p with FUT8 mRNA, by analysis of 27 hepatocellular carcinoma tissue samples using qRT-PCR." (PMID 36699698, 2022). "Since FUT8 is the only fucosyltransferase that catalyzes the formation of core fucosylation in mammals, therefore, the human hepatoma HepG2 wild-type (WT) and HepG2 FUT8 KO cells were used to clarify the hepatic protective mechanism of 2FF in vitro." (PMID 36120347, 2022). "In fact a recent report demonstrated that Fut8-null mice exhibited reduced cancer growth in a chemical-induced hepatoma model." (PMID 27136596, 2016). "The increased expression of FUT8 and the extent of core fucosylation are reported to be altered under pathological conditions such as hepatocellular carcinoma and liver cirrhosis, and is strongly linked to age-related changes in glycosylation in the liver." (PMID 26747427, 2016). "Moreover FUT8 upregulation also has been described in various cancer pathologies like hepatocellular carcinoma, pancreatic, breast, lung and colorectal cancer or in epithelial-mesenchymal transition." (PMID 36699698, 2022). "Interestingly, other studies in hepatocellular carcinoma models show slightly different responses to modulation of FUT8, where knockdown in HepG2 cells suppressed cell proliferation, migration, and tumor growth." (PMID 31126011, 2019). "Moreover, Fut8 or core fucose is aberrantly upregulated in several types of cancer in addition to hepatoma and lung cancer, such as breast and prostate cancers." (PMID 27136596, 2016). "Epigenetic analyses have revealed low levels of FUT8 methylation in cancers such as hepatocellular carcinoma, suggesting that the most relevant part of FUT8 regulation may be at the transcriptional and post-transcriptional levels, a largely unexplored area of investigation." (PMID 36980181, 2023). "Ectopic expression of FUT8 resulted in the steatosis-like phenotype in transgenic mice, while on the other hand, knocking out FUT8 in mice was reported to dramatically decrease the postnatal survival and inhibition of chemical-induced hepatocellular carcinoma and tumorigenesis." (PMID 29339807, 2018). "In comparative immunoprecipitation analyses of NTCP between HB611 cells and Fut8-knockdown HB611 cells followed by mass spectrometry, we identified myosin hyper 9 (MYH9) as a key molecule in the NTCP-mediated entry of BNCs into hepatoma cells." (PMID 34578441, 2021). "Our recent studies showed that α1,6-fucosyltransferase (FUT8), a key glycosyltransferase, was the most up-regulated glycosyltransferase after the HCV infection of human hepatocellular carcinoma Huh7.5.1 cells." (PMID 31022917, 2019). "Since Fut8 is aberrantly elevated in hepatocellular carcinoma compared with nearly no expression in normal liver, we can assume that liver-derived core fucosylated proteins in serum would be utilized for the diagnosis of liver cancer." (PMID 27136596, 2016). "By contrast, the negative coefficient for FUT8 implies a reduction in alpha-1,6 fucosylation (core fucosylation) after IL-6 stimulation, which does not contradict our previous finding that FUT8 overexpression does not facilitate cellular fucosylation in hepatoma cells." (PMID 36313594, 2022).